TRAV27 (T cell receptor alpha variable 27)
Description:
V region of the variable domain of T cell receptor (TR) alpha chain that participates in the antigen recognition. Alpha-beta T cell receptors are antigen specific receptors which are essential to the immune response and are present on the cell surface of T lymphocytes. Recognize peptide-major histocompatibility (MH) (pMH) complexes that are displayed by antigen presenting cells (APC), a prerequisite for efficient T cell adaptive immunity against pathogens. Binding of alpha-beta TR to pMH complex initiates TR-CD3 clustering on the cell surface and intracellular activation of LCK that phosphorylates the ITAM motifs of CD3G, CD3D, CD3E and CD247 enabling the recruitment of ZAP70. In turn, ZAP70 phosphorylates LAT, which recruits numerous signaling molecules to form the LAT signalosome. The LAT signalosome propagates signal branching to three major signaling pathways, the calcium, the mitogen-activated protein kinase (MAPK) kinase and the nuclear factor NF-kappa-B (NF-kB) pathways, leading to the mobilization of transcription factors that are critical for gene expression and essential for T cell growth and differentiation. The T cell repertoire is generated in the thymus, by V-(D)-J rearrangement. This repertoire is then shaped by intrathymic selection events to generate a peripheral T cell pool of self-MH restricted, non-autoaggressive T cells. Post-thymic interaction of alpha-beta TR with the pMH complexes shapes TR structural and functional avidity.
Synonyms: TCRAV10S1; TCRAV27S1
Gene: T-cell receptor variable (V) gene on chromosome 14 (22,147,995 to 22,148,633, forward strand). Ensembl gene ENSG00000211809.
Subcellular location: Cell membrane
Gene Ontology:
Molecular function: protein binding
Biological process: defense response to Gram-positive bacterium; immune response; response to bacterium
Cellular component: alpha-beta T cell receptor complex; plasma membrane
Homologues: Orthologues: mouse Trav18 (61% identical). Paralogues in human: TRAV25 (58% identical), TRAV34 (47% identical), TRAV17 (44% identical), TRAV6 (41% identical), TRAV10 (40% identical), TRAV39 (40% identical), TRAV20 (39% identical), TRAV30 (39% identical), TRAV21 (37% identical), TRAV36DV7 (37% identical), TRAV7 (36% identical), TRAV24 (35% identical), and 11 more.
Diseases named in the same sentence as TRAV27 in open-access papers:
TRAV27 is named in the same sentence as 2 diseases in open-access papers, as found by Europe PMC text mining. Sharing a sentence is not in itself a finding about the gene and the disease. The quoted sentences say what the papers report.
influenza (1 paper, 2018). An acute viral infection of the respiratory tract, occurring in isolated cases, in epidemics, or in pandemics; it is caused by serologically different strains of viruses (influenzaviruses) designated A, B, and C, has a 3-day incubation period, and usually lasts for 3 to 10 days. "Importantly, these TRAV27/TRBV19 TCRs display the key motifs for A2+M158 epitope recognition, similar to those found in adults, tissues, and influenza-infected patients." (PMID 29997621, 2018).
Sepsis (1 paper, 2024). Sepsis is defined as life-threatening organ dysfunction caused by a dysregulated host response to infection. "In addition, TRAV27 was over-represented, while TRAV8-1 and TRAJ37 were down-regulated in the E-SEP group compared to the Y-SEP group, which might indicate abnormalities in TCR repertoires in elderly patients with sepsis." (PMID 38909272, 2024).